MDC1 (mediator of DNA damage checkpoint 1)
Diseases named in the same sentence as MDC1 in open-access papers (continued):
Sharing a sentence is not in itself a finding about the gene and the disease.
cancer (continued). "If ATM-phosphorylated MDC1 does not require RNF8 to mediate cisplatin resistance, we anticipated that the depletion of RNF8 alone would not change the si-MDC1-induced cisplatin sensitivity in BIN1-deficient cancer cells." (PMID 34948122, 2021). "Overexpressed Rad51, BRCA1, and MDC1 contribute to genomic integrity and chemoresistance in cancer." (PMID 34025420, 2021). "We next investigated whether MDC1, immediately downstream of γH2AX, determines cisplatin resistance in BIN1-deficient cancer cells." (PMID 34948122, 2021). "MDC1 majorly functions as a mediator in the DDR, which mediates the recruitment of other DDR proteins, such as ataxia telangiectasia-mutated (ATM), Breast Cancer 1, Early Onset (BRCA1), Mre11/Rad50/NBS1 (MRN) complex, to the site of damage." (PMID 25198518, 2014). "Genomic instability and cancer susceptibility are increased in the absence of Mdc1, Rnf8, 53bp1 or Brca1." (PMID 21552324, 2011). "However, it remained unclear how the MDC1 cleavage by caspase-3 could be prohibited in cisplatin-resistant cancer cells." (PMID 34948122, 2021). "Thus, our findings suggest that c-Fos/miR-22/MDC1 might act as a sensitizer in cancer therapy and accompany anticancer drug or radiation therapy to enhance therapeutic efficacy and to improve the chance recovery from cancer." (PMID 28637007, 2017). "Mediator of DNA damage checkpoint protein 1 (MDC1) plays an early and core role in Double-Strand Break Repair (DDR) and ataxia telangiectasia-mutated (ATM) mediated response to DNA double-strand breaks (DSBs), and thus involves the pathogenesis of several DNA damage-related diseases such as cancer." (PMID 25198518, 2014). "This enhances the assembly of activated DGCR8 and RNF168 at DSB sites via MDC1, promoting DSB repair and contributing to radioresistance in cancer cells." (PMID 38702734, 2024). "Taken together, AP4-induced MDC1 therefore limits the extent of DNA damage that cells encounter after activation of c-MYC and thereby allows the proliferation of cancer cells with deregulated c-MYC expression." (PMID 35624466, 2022). "BMX, BMPR1B, BTK, and MDC1 belong to the COSMIC_mut gene set, and CSNK2A2 belongs to the COSMIC_other gene set, while ASH2L belongs to the non-cancer gene set." (PMID 19765316, 2009). "Hence, our work reveals a previously unknown function of MDC1 in RF biology, a role that contributes to DNA damage induced by genotoxic agents and the response of BRCA1- or BRCA2-deficient tumors to clinically relevant anti-cancer drugs, such as PARPi and cisplatin." (PMID 41408464, 2026). "In this regard, MDC1, a mediator protein activated as part of ATM-ChK2 pathway is necessary for proper manifestation of the DDR response and can be a limiting factor affecting prognosis of certain cancers." (PMID 32160908, 2020). "Reference-based analysis of these target genes based on their potential roles in regulating DNA damaging responses and cancer progression led us to select SUZ-12 (polycomb repressive complex 2) and MDC-1 (mediator of DNA-damage checkpoint 1) as key target genes of miR-489." (PMID 32784600, 2020). "Additionally, USP15, recruited to DSBs by MDC1, deubiquitinates BARD1, a BRCA1 binding partner, facilitating the interaction between BARD1 and HP1γ at DSBs, thus enhancing olaparib resistance in cancer cells." (PMID 38702734, 2024).
cancer (continued). "Five genes are involved in DNA repair, a role closely related to genome maintenance and cancer, and were shown to have a protective role in various types of cancer (only one paper is cited by gene, but many others confirm this role): EXO1, ERCC1, GTF2H1, MDC1, and DGCR8." (PMID 31568528, 2019). "Thus, we suggest that the c-Fos/miR-22/MDC1 axis-mediated downregulation of DSB repair induces chromosome instability during terminal differentiation and may represent a therapeutic target for cancer." (PMID 28637007, 2017).
tumor (32 papers, 2013 to 2026). "Together, these findings show that loss of MDC1 counteracts the efficacy of PARPi in BRCA1/2-deficient tumor cells both in vitro and in vivo." (PMID 41408464, 2026). "Many nuclear proteins containing FHA domains, like AGGF1, CHK2, and MDC1, transcriptionally regulate the expression of genes associated with cell cycle checkpoints, DNA repair, and apoptosis to achieve their tumor suppression function." (PMID 37452081, 2023). "IF staining with anti‐γH2AX or anti‐MDC1 antibody showed that tumor cells rescued with rPKM2 S222A had much less γH2AX and MDC1 foci than the cells rescued with rPKM2 WT after etoposide treatment." (PMID 35048565, 2022). "We verified the increased RNA expression of MMEJ-related H2ax, Fen1, Cdk1, Plk1, and Polθ and decreased RNA expression of Mdc1 in the MmuPV1 tumor tissues by real-time RT-qPCR." (PMID 34343212, 2021). "MDC1 has been known as a vital mediator of the repair of DSB which takes part as an important tumor suppressor via its DNA damage repair function." (PMID 28868264, 2017). "Patients with tumor stages < pT3 possessed 10.9 cells/μl MDC1 and 5.11 cells/μl PDC, while 7.8 cells/μl MDC1 and 4.51 cells/μl PDC were present in the advanced RCC stages ≥ pT3." (PMID 24995120, 2014). "Nowadays, more and more evidences supported MDC1 to be a potential tumor suppressor with roles in repairing DNA damage and inhibiting tumor growth." (PMID 25198518, 2014). "MDC1 are potent cross-presenters of antigens to activate Th1 and CD8+ T lymphocytes and may associate with an improved anti-tumor immune response." (PMID 35626676, 2022). "An overexpression of MDC-1 has been shown to mediate tumor resistance to anticancer agents." (PMID 33922992, 2021). "In addition, there was a trend for a positive correlation of IL-8 and IP-10/CXCL10 with perivascular CD163+ cell infiltrates as well as a trend for a positive correlation of the percentage of CD163+ cells and MDC-1/CCL22 in the tumor core." (PMID 34654395, 2021). "MDC1 is a tumor suppressor that interacts with Rad51 to facilitate HR repair." (PMID 34880209, 2021). "Since up-regulation of c-MYC is a hallmark of CRCs, it is therefore tempting to speculate that CRCs harbor comparatively high levels of DNA damage due to elevated expression of c-MYC, which results in a requirement of MDC1 up-regulation for tumor initiation and progression." (PMID 35624466, 2022). "Just 19 (21.1%) had MDC1 and 25 (27.8%) MDC2 tumours, and 11 (12.2%) presented with leptomeningeal metastasis (LM+)." (PMID 35159015, 2022). "We analyzed the protein expression of MRE11, MDC1, ATM, ATR and BRCA1 by immunohistochemistry (IHC) in 97 SOC samples, and correlated with clinical parameters including age, tumor grades, clinical stage, status of menstruation and chemotherapy." (PMID 24752797, 2014). "Furthermore, cDC1 acquiring ZsGreen from tumours in the lungs also showed increased upregulation of PDL1 and this was reflected in both mDC1 and rDC1 populations." (PMID 37478193, 2023).
tumor (continued). "To further investigate whether the PARPi resistance can be recapitulated in vivo, we expressed the non-targeting (NT) or Mdc1-targeting gRNAs in the KB2P tumor-derived organoids and grafted them orthotopically into a mammary gland of mice." (PMID 41408464, 2026). "However, the Bora N terminal fragment failed to sensitize tumor cells to IR treatment, indicating that the interaction between Bora and MDC1 is necessary for the radiosensitization effect of Bora." (PMID 25742493, 2015). "Interestingly, the well-known tumour suppressor and DSB repair protein BRCA1, whose optimal relocalisation to subnuclear foci at DNA lesions requires MDC1 (in the presence of DSBs) and a proficient FANC pathway (in response to ICLs), was recently shown to be involved in the response of cells to UVC." (PMID 23365640, 2013).
infection (7 papers, 2014 to 2022). The state of being infected such as from the introduction of a foreign agent such as serum, vaccine, antigenic substance or organism. "It has been reported that upon infection with either WT or an E4-deleted Ad, Mdc1, an early participant in irradiation-induced DDR, accumulated in foci before synthesis of the Ad DBP protein was detected." (PMID 32906746, 2020). "While there were no significant perturbation in the protein levels, enhanced phosphorylation of Nbs1, MDC1, 53BP1, representing the activated forms, was evident upon Rv infection (Shiloh, 2003)." (PMID 32223892, 2020). "The DDR adaptor molecule MDC1, which dimerizes to bridge the DNA-break sensing MRN complex and γH2AX chromatin marks, remains distinct from MVM APAR bodies during infection." (PMID 33064772, 2020). "This yet unproven hypothesis is supported by the finding that DDR sensors and effectors such as Mre11, Mdc1, and ATM colocalized with viral genomes early during infection." (PMID 32906746, 2020). "Interestingly, since NS1 is not present in the early steps of infection, other proteins such as the viral protein of the capsid or the cellular proteins CTCF or MDC1, may be involved if localization of MVM at DNA damage sites occurs at the earliest stage of infection." (PMID 35216038, 2022).
MDC1 also shares sentences with these, for which no sentence is quoted: chronic myelogenous leukaemia (2 papers); autoimmune thyroid disease (1); brain tumors (1); dyskeratosis congenita (1); esophageal adenocarcinoma (1); Familial adenomatous polyposis (1); Fanconi anemia complementation group C (1); fatty liver disease (1); female infertility (1); glioma (1); hypertriglyceridemia (1); muscular dystrophy (1); myeloma (1); myopathies (1); Obesity (1); pancreatic NECs (1); pancreatic NETs (1); progressive multifocal leukoencephalopathy (1); prostate tumors (1); proteinopathy (1); sarcoglycanopathies (1); Sepsis (1); skin cancer (1); thyroid cancer (1); viral infections (1); vitamin B12 deficiency (1); Werner syndrome (1).